U3 (Small nucleolar RNA U3 )
Synonyms: LOC124901509
Gene: Small nucleolar RNA gene on chromosome 6 (75,398,860 to 75,399,067, reverse strand). Ensembl gene ENSG00000221332.
Gene Ontology:
Biological process: RNA processing
Cellular component: nucleolus
Homologues: Orthologues: chimpanzee U3 (99% identical), macaque U3 (92% identical), pig U3 (69% identical), dog U3 (54% identical). Paralogues in human: SNORD3P1 (76% identical), U3 (75% identical), U3 (73% identical), SNORD3H (73% identical), SNORD3E (72% identical), U3 (72% identical), U3 (71% identical), SNORD3G (71% identical), U3 (70% identical), U3 (69% identical), U3 (68% identical), SNORD3D (68% identical), and 9 more.